RN7SKP118 (RN7SK pseudogene 118)
Gene: Miscellaneous RNA gene on chromosome 16 (67,321,658 to 67,321,987, reverse strand). Ensembl gene ENSG00000201201.
Homologues: Orthologues: chimpanzee 7SK (99% identical), guinea pig 7SK (88% identical). Paralogues in human: 7SK (90% identical), RN7SKP187 (85% identical), RN7SKP48 (81% identical), RN7SKP174 (81% identical), RN7SKP227 (81% identical), RN7SKP292 (80% identical), RN7SKP185 (80% identical), RN7SKP178 (79% identical), RN7SKP55 (79% identical), RN7SKP62 (79% identical), RN7SKP76 (78% identical), RN7SKP81 (77% identical), and 284 more.